Y_RNA (Y RNA )
Gene: Miscellaneous RNA gene on chromosome X (108,676,951 to 108,677,057, reverse strand). Ensembl gene ENSG00000207146.
Homologues: Orthologues: chimpanzee Y_RNA (99% identical), macaque Y_RNA (95% identical). Paralogues in human: RNY1 (90% identical), Y_RNA (90% identical), Y_RNA (88% identical), Y_RNA (87% identical), Y_RNA (86% identical), Y_RNA (85% identical), RNY1P11 (84% identical), Y_RNA (84% identical), RNY1P8 (83% identical), Y_RNA (83% identical), RNY1P12 (82% identical), Y_RNA (82% identical), and 99 more.